PSMB5 (proteasome 20S subunit beta 5)
Diseases named in the same sentence as PSMB5 in open-access papers (continued):
Sharing a sentence is not in itself a finding about the gene and the disease.
endothelial dysfunction (2 papers, 2021 to 2025). In vascular diseases, endothelial dysfunction is a systemic pathological state of the endothelium (the inner lining of blood vessels) and can be broadly defined as an imbalance between vasodilating and vasoconstricting substances produced by (or acting on) the endothelium. "Promote the expression of PSMB5, inhibit ROS production and Drp1 in a Nrf2 dependent manner, thereby inhibiting mitochondrial fission and improving endothelial dysfunction." (PMID 34307357, 2021).
multiple sclerosis (2 papers, 2019 to 2024). A progressive autoimmune disorder affecting the central nervous system resulting in demyelination. "Other genes related to translation and proteasome complex were also strongly associated to such diseases, such as PSMB5 with multiple sclerosis (Pascal gene score: p-value = 0.0348) and HDL cholesterol (Pascal gene score: p-value = 0.0155)." (PMID 31269015, 2019).
osteosarcoma (2 papers, 2021 to 2024). A usually aggressive malignant bone-forming mesenchymal neoplasm, predominantly affecting adolescents and young adults. "A recent study stated that upregulation of the PSMB5 gene in osteosarcoma cell line (~295 nTPM) with an upregulated PSMB5 gene correlation was observed with the increase in the resistance of these cells to the bortezomib treatment." (PMID 38339421, 2024).
squamous cell carcinoma (2 papers, 2016 to 2025). A carcinoma arising from squamous epithelial cells. "Notably, thymic carcinomas differed from squamous cell carcinomas in other organs by higher levels of β5i (PSMB8) and constitutive proteasome β5 (PSMB5)." (PMID 41339338, 2025). "Furthermore, we were able to show that TC are distinguished from histologically similar squamous cell carcinomas in other organs (e.g., lung and head and neck) by their increased expression of the immunoproteasome β5i (PSMB8) subunit together with high levels of the CPS subunit β5 (PSMB5)." (PMID 41339338, 2025).
Type 1 Diabetes (2 papers, 2024 to 2025). "PSMB5 overexpression exhibited particularly strong enrichment in autoimmune-related pathways, including type I diabetes mellitus, transplant rejection mechanisms, and thyroid autoimmunity, along with taurine metabolism." (PMID 40826785, 2025). "We explored differences in the DNA methylation statuses of PSMA6, PSMB5, HIF1A, and KEAP1 gene promoter regions in patients with type 1 diabetes and different diabetic retinopathy (DR) stages." (PMID 38927561, 2024).
Alzheimer disease (1 paper, 2019). A progressive, neurodegenerative disease characterized by loss of function and death of nerve cells in several areas of the brain leading to loss of cognitive function such as memory and language. "We combined this hub gene analysis with GWAS association gene scores, and observed that PSMB5, UBE2L3, and PSMD3 are important in many age-related diseases or phenotypes, such as Alzheimer’s disease, HDL cholesterol, LDL cholesterol, triglycerides, and insulin resistance." (PMID 31269015, 2019).
chordoma (1 paper, 2023). Chordomas are rare malignant tumors arising from embryonic remnants of the notochord in axial skeleton. "Our data show a significant increased expression for both PSMB5 and PSMB8 subunits in these two chordoma cells compared to both HEK-293 and HUVEC cells." (PMID 37111759, 2023). "For the first time, we performed the gene expression analysis for proteasomal subunits PSMB5 and PSMB8, and found that these two subunits are increased in chordoma." (PMID 37111759, 2023). "Furthermore, we found that proteasomal subunits proteasome 20S subunit beta 5 (PSMB5) and proteasome 20S subunit beta 8 (PSMB8) upregulated in two human chordoma cell lines, U-CH1 and U-CH2." (PMID 37111759, 2023). "Proteasomal subunits PSMB5 and PSMB8 are highly upregulated in chordoma cell lines U-CH1 and U-CH2: As we found, proteasomal inhibitors as one class of the hits from primary screening; next, we asked whether proteasomal subunits are increased in chordoma." (PMID 37111759, 2023). "Furthermore, we discovered that proteasomal subunits PSMB5 and PSMB8 are increased in human chordoma cell lines U-CH1 and U-CH2, confirming that the proteasome may serve as a molecular target whose specific inhibition may lead to better therapeutic strategies for chordoma." (PMID 37111759, 2023).
coronary artery disease (1 paper, 2019). "Although only the PSMB5 gene was an experimentally validated candidate gene in mice, the PSMD3 gene was related with coronary artery disease, HDL cholesterol and fasting proinsulin, and would also be worthwhile to explore further." (PMID 31269015, 2019).
esophageal cancer (1 paper, 2025). A primary or metastatic malignant neoplasm involving the esophagus. "PSMB5 is mechanistically associated with oncogenesis in several malignancies, especially in breast, prostate, and esophageal cancers." (PMID 41409300, 2025).
hypersomnia (1 paper, 2023). A sleep disorder characterized by excessive sleepiness. "Six (GPX4, PSMB5, PSMB6, PRDX5, ASNA1, EIF4H) out of seven hub genes were associated with the expression of insomnia/hypersomnia only in females, while UROD was the only hub gene common to both sexes." (PMID 37884562, 2023).
invasive breast carcinoma (1 paper, 2016). A carcinoma that infiltrates the breast parenchyma. "Intriguingly, we found that tumor samples from patients with invasive breast carcinoma exhibited significantly lower PSMB2 and PSMB5 proteasome subunit mRNA expression compared to samples derived from normal tissue." (PMID 26930717, 2016).
ischemic stroke (1 paper, 2021). A stroke disorder caused by obstruction of blood flow to the brain, due to thrombotic (local blood clot formation) or embolic (due to a blood clot or other material traveling from another site) event. "To evaluate the expression levels of Psmd3 and PSMB5 in the peri‐ischemic samples, we carried out Western blotting to see whether their protein levels were altered in ischemic stroke in mice." (PMID 33369048, 2021).
liposarcoma (1 paper, 2021). A usually painless malignant tumor that arises from adipose tissue. "Moreover, PSMB5, the target of bortezomib and carfilzomib, was found overexpressed in liposarcoma patient samples in comparison to normal adipose tissue." (PMID 32851475, 2021).
lymph node metastasis (1 paper, 2025). "Consequently, we meticulously analyzed the relationship between PSMB5 expression and lymph node metastasis in all three cell lines, discovering substantial statistical differences for endothelial cells (p < 0.0001) and fibroblasts (p < 0.0001)." (PMID 41409300, 2025).
ocular hypertension (1 paper, 2015). Abnormally high intraocular pressure. "Analogous to wild-type and E50K optineurin transduced eyes, an enhanced optineurin, reduced PSMB5 and increased LC3 staining was observed in the RGC layer of sections from injury grades 2.75 and 5 compared to injury grade 1.0 (normal) in the rat ocular hypertension model." (PMID 25943884, 2015).
pterygium (1 paper, 2018). A wedge-shaped fibrovascular lesion arising from the bulbar conjunctiva and extending to the cornea. "The Oltipraz caused an enhancement of PSMB5 expression, indicating that the expression of this subunit in pterygium fibroblasts is indeed mediated by Nrf2/ARE pathway." (PMID 30563490, 2018). "It was observed that UVB irradiation, which exhibited very low deleterious effect on cell viability, caused significant down-regulation of PSMB5 in pterygium fibroblasts in a radiation dose-depended mode." (PMID 30563490, 2018). "This may be attributed to UVB irradiation which has a suppressive effect on PSMB5 expression in pterygium fibroblasts, which in turn are known to be implicated in pterygium pathogenesis." (PMID 30563490, 2018). "The expression of PSMB5 at the mRNA level in pterygium and normal conjunctival tissues was examined using RT-PCR." (PMID 30563490, 2018). "In the present study we investigated the effect of UVB irradiation on β5 proteasome subunit (PSMB5) expression and activity in pterygium fibroblasts." (PMID 30563490, 2018). "In the present study we have shown that the expression of PSMB5 in pterygium is lower than that in normal conjunctiva." (PMID 30563490, 2018). "RT-PCR analysis showed that the expression of PSMB5 was significantly lower in pterygium than in normal conjunctiva." (PMID 30563490, 2018). "The expression of PSMB5 in pterygium tissues was statistically significantly lower than normal conjunctiva." (PMID 30563490, 2018). "We also present evidence on the effect of UVB irradiation on PSMB5 expression and activity in pterygium fibroblasts." (PMID 30563490, 2018). "Since the PSMB5 expression in pterygium fibroblasts is mediated by the Nrf2/ARE pathway, it would be expected that the suppression of Nrf2 expression by UVB irradiation to be about at the same levels with the suppression caused by UVB on PSMB5 expression." (PMID 30563490, 2018). "In pterygium fibroblasts, UVB exposure leads to down-regulation of Nrf2/ARE-mediated PSMB5 gene expression, in which src kinases may be implicated." (PMID 30563490, 2018). "This study investigates the expression of PSMB5 in pterygium and the effect of UVB irradiation on its expression and activity in pterygium fibroblasts." (PMID 30563490, 2018). "Since the expression of PSMB5 is mediated by Nrf2/ARE pathway in various cell species, we investigated whether the same occurs in pterygium fibroblasts." (PMID 30563490, 2018). "In order to examine whether the same applies to pterygium fibroblasts, cells were irradiated with UVB after pre-incubation with src kinase inhibitor PP2, at radiation doses 0–50 mJ/cm2, and the expression of PSMB5 and Nrf2 at the mRNA level was examined using RT-PCR." (PMID 30563490, 2018). "UVB-irradiation had the same effect, but to a lower extent, on PSMB5 expression in normal conjunctival fibroblasts, indicating that the observed effect of UVB-irradiation on pterygium fibroblasts was not the result of degeneration of these cells due to irradiation." (PMID 30563490, 2018).
cancer (49 papers, 1988 to 2026). A tumor composed of atypical neoplastic, often pleomorphic cells that invade other tissues. "The dipeptide compound, BTZ, reversibly inhibits the chymotrypsin-like catalytic activity of the 20S complex, associating with PSMB5 subunit and suppressing proliferation of numerous cancer types." (PMID 39655950, 2025). "Proteasome 20S subunit beta 5 (PSMB5) is increased in various cancers, and its mutation leads to resistance to proteasomal inhibitors." (PMID 37111759, 2023). "Consistent with other cancers, PSMB5, TPR, and PRPF19 were independent prognostic risk factors in BCa, while PSMD14 seemed to be a protective factor, which was different from other types of cancers." (PMID 35898492, 2022). "To test PASTMUS strategy in mapping functional elements of proteins, we selected three genes (ANTXR1, CSPG4, and HBEGF) encoding bacterial toxin receptors and three genes (HPRT1, PLK1, and PSMB5) encoding cancer drug targets." (PMID 31842968, 2019). "We further quantified that 12% of cancer‐linked genes were T‐cell enriched, among which EIF5A and PSMB5 are targets of anticancer drugs under clinical trial investigation." (PMID 41216857, 2025). "Another potential strategy to overcome drug resistance in cancer therapy is to target the 19S regulatory complex instead of the 20S core complex (such as PSMB5), which is the target of standard proteasome inhibitors such as bortezomib." (PMID 36498916, 2022). "Evidence has also demonstrated that silence of PSMB5 promotes the activation of M1 macrophages in vitro, which indicates the dual role of PSMB5, and its potential impact on cancer immunotherapy." (PMID 36358759, 2022). "In contrast, overexpression of PSMB5, an important catalytic site in the proteasome, was associated with decreased OS and PFI in 36% and 27% of cancer types, respectively." (PMID 36123629, 2022). "Because of the important role of PSMB5 in mediating proteasome function, the abnormal expression of PSMB5 reflected the dysfunction of the whole proteasome complex in cancer." (PMID 36062301, 2022). "Potentially, through inhibiting Sm gene expression, the loss of proteasomal activity can be achieved with similar cytotoxic effects as observed when targeting PSMB5, but with more selectivity towards cancer cells." (PMID 32545483, 2020). "To compare the functional maps with their corresponding protein structures, we highlighted those critical residues identified from PASTMUS on the surface diagram of three cancer drug targets (PSMB5, PLK1, and HPRT1)." (PMID 31842968, 2019). "In human patients, the anti-cancer drug BTZ inhibits the proteolytic activity of the proteasome subunit beta 5 (PSMB5), and, to a lesser extent, also the beta 1 subunit (PSMB1)." (PMID 25474446, 2014). "MR further validated that PSMB5 is a crucial pro-cancer factor for BLCA." (PMID 41409300, 2025). "Again, the independent cancer genomics bioinformatic approach confirmed Psmb5 as the top candidate." (PMID 29515774, 2018). "A survey of public available data bases (COSMIC, canSAR, Cancer Cell Line Ecyclopedia) indicated that PSMB5 and PSMB7 genes are not mutated, deleted nor amplified in REC1 cells." (PMID 28797244, 2017). "Based on transcriptomic analyses of thousands of samples from The Cancer Genome Atlas, we report that expression of constitutive proteasome (CP) genes (PSMB5, PSMB6, PSMB7) and immunoproteasome (IP) genes (PSMB8, PSMB9, PSMB10) is increased in most cancer types." (PMID 27659694, 2016). "Collectively, this study prioritizes PSMB5 and PSMB6 as consistently associated functional biomarkers that integrate genetic dependency and immune context, providing a data-driven framework for stratifying proteasome-targeted therapeutic strategies across cancers." (PMID 42280256, 2026). "Intriguingly, overexpression of one of the three proteasome catalytic sites, PSMB5, had an adverse effect on prognosis in 12 (OS) and 9 (PFI) of the studied cancer types." (PMID 36123629, 2022).
cancer (continued). "In comparison to other cancer types, STS showed high expression of PSMB5, PSMB6 and PSMB7, the subunits of the constitutive proteasome and low levels of PSMB8, PSMB9 and PSMB10, the subunits specific to immunoproteasomes." (PMID 32851475, 2021). "Furthermore, co-amplification of PSM genes located in close proximity to one another (e.g. PSMB5 and PSMB11, 14q11.2; PSMB4 and PSMD4, 1q21.3; PSMB8 and PSMB9, 6p21.32) or known cancer drivers (e.g. co-amplification of ERBB2 and PSMB3) were also frequently amplified together." (PMID 36123629, 2022).
tumor (47 papers, 2012 to 2025). "Specifically, most regions of the primary tumour exhibited an upregulation of genes positively linked to resistance (e.g., PSMB5 and MSSB2) and a downregulation of genes negatively associated with resistance." (PMID 41168392, 2025). "In this study, we predicted candidate genes targets of miR-1229, among which PRRG4, REEP5, and PSMB5 were associated with a poor prognosis and highly expressed in tumor tissues." (PMID 33854621, 2021). "Moreover, the association between PSMB5 expression and the genes sets of immune cells implied a critical role of PSMB5 in regulating tumor immunology in HCC." (PMID 36062301, 2022). "This condition may also arise in hematologic tumor cells with acquired resistance to bortezomib due to the acquisition of mutations in the PSMB5 gene encoding the constitutive β5 subunit." (PMID 24418325, 2014). "Second, the constitutive β5 subunit is structurally altered in all 3 bortezomib-resistant tumor cell lines due to mutations in the PSMB5 gene introducing single amino acid substitutions (e.g. Ala49Thr) in the bortezomib-binding pocket leading to diminished bortezomib binding efficiency." (PMID 24418325, 2014). "Subsequent in vitro functional tests demonstrated that PSMB5 knockdown significantly impeded tumor cell growth and migration while markedly promoting apoptosis." (PMID 41409300, 2025). "A study by Vangalaet al. revealed that PSMB5 is a target of STAT3 that has been tested in other tumor cells." (PMID 38009004, 2023). "G3-MB tumor cells were found to exhibit stronger PSMB5 expression than tumor cells of the other three MB subtypes at single-cell level." (PMID 36273157, 2022). "Aberrant expression of PSMB5 is correlated to tumor cell proliferation metastasis and drug resistance." (PMID 36062301, 2022). "Reported mechanisms include overexpression or mutations in PSMB5 (the proteasomal target of BTZ), P-glycoprotein expression (efflux pump), microenvironmental upregulation of IL-6, IGF-1, or tumor upregulation of HSP90, PI3K, MYC, and IGF-1." (PMID 26254279, 2015). "The findings suggest that further research on PSMB5 may reveal new pathways involved in bladder carcinogenesis, and that targeted suppression of PSMB5 expression could potentially enhance tumor cell sensitivity to chemotherapy." (PMID 41409300, 2025). "All these results showed that PSMB5 might play a protective role in the tumor development of ccRCC, further researches are needed to add to the evidences and investigate the potential mechanisms." (PMID 35693739, 2022). "In addition to its association with poor survival in HCC, PSMB5 mRNA expression was significantly higher in tumor tissues of HCC patients compared with matched non-tumor liver tissues." (PMID 41305476, 2025). "Bortezomib could target PSMD2, PSMB1 and PSMB5 to inhibit the proteasome degradation of cell cycle check points, to block cell proliferation and tumor growth of NSCLC, which was potential optional drug for NSCLC patients with different driven mutations or with TKI resistance." (PMID 37864031, 2023). "Moreover, the tumor cell subpopulations expressing the highest level of PSMB5 (GP3-B1) are different from the ones of MYC, OTX2 or CRX (GP3-B2 for MYC, GP3-C2 for OTX2 and CRX), further supporting the involvement of unidentified SE-associated TFs in regulating PSMB5 transcription in G3-MB." (PMID 36273157, 2022). "PSMB5 inhibition reduced formed colonies and migration in MDA-MB-231 cells and suppressed tumor growth at early stages in in vivo." (PMID 37529110, 2023). "Next, dual inhibition of PSMB5 and PSMB7 were performed in tumor cells using a combination of each specific siRNA at a suboptimal dose." (PMID 29515784, 2018). "Similarly, PSMB5 and MTSS2 were expressed higher in the snRNA-Seq tumour cells." (PMID 41168392, 2025).
tumor (continued). "In the analysis of gene expression in whole proteasomes including PSMB5 (β5), PSMB8 (iβ5), PSMB7 (β2), PSMB10 (iβ2), PSMB6 (β1), and PSMB9 (iβ1), these genes alternated or showed only slight in their expression following silencing of PSMB5 or PSMB7 in three tumor cells." (PMID 29515784, 2018). "The role of PSMB5 is less clear, as a series of 92 primary DLBCL showed no sign of this protein in the tumor cells, except within the microenvironment of the tumor, which could be explained with a possible secretion from the tumor cells into the stroma." (PMID 36291816, 2022).
neurodegenerative disease (3 papers, 2023 to 2025). A disorder of the central nervous system characterized by gradual and progressive loss of neural tissue and neurologic function. "Proteasome activity, particularly the chymotrypsin-like (CT-like) activity mediated by the β5 catalytic subunit encoded by Proteasome Subunit Beta Type-5 (PSMB5), has been shown to decline with age and in the context of PD and other neurodegenerative diseases." (PMID 41436906, 2025).
inflammatory myopathies (2 papers, 2014 to 2020). "Expression of constitutive (PSMB5, -6, -7) and corresponding immunoproteasomal subunits (PSMB8, -9, -10) was analyzed by real-time RT-PCR in muscle biopsies and sorted peripheral blood cells of patients with IIM, non-inflammatory myopathies (NIM) and healthy donors (HD)." (PMID 25098831, 2014).